ERCC1 (ERCC excision repair 1, endonuclease non-catalytic subunit)
Diseases named in the same sentence as ERCC1 in open-access papers (continued):
Sharing a sentence is not in itself a finding about the gene and the disease.
melanoma (continued). "Standard chemotherapeutics, such as cisplatin, are ineffective on metastatic melanoma and we, and others, have shown that levels of a number of NER proteins in melanoma cells are elevated in response to cisplatin: ERCC1 and XPF, XPC and DDB2, XPA (this publication)." (PMID 29254481, 2017). "Omega-3 PUFAs also drive the expression of ERCC1, DUSP6, and p-ERK, which activates ERCC1 and thereby improves the anti-tumor action of CDDP against melanoma cells." (PMID 34829495, 2021). "Two candidate inhibitors of ERCC1-XPF (E-X PPI2 and E-X AS7) reduced the ERCC1-XPF expression level, suppressed the NER process, and sensitized melanoma to cisplatin treatment." (PMID 34026617, 2021). "Enhanced melanoma cell sensitivity to cisplatin, inhibition of NER activity, and decreased level of ERCC1-XPF heterodimers in ovarian cancer cells were observed after E-X PPI2 or E-X AS7 usage." (PMID 32370233, 2020). "Small molecule inhibitors of the ERCC1-XPF complex have been developed and shown to potentiate cisplatin efficacy in the A375 melanoma cell line and H460 and H1299 lung cancer cell lines." (PMID 29373959, 2018). "In another study, Compound AS5-4 disrupted ERCC1/XPF activity and enhanced cisplatin sensitivity in a melanoma cell line." (PMID 30400270, 2018). "We further exploited a peptide containing this dimerization domain to destabilise both endogenous ERCC1 and XPF, resulting in major reductions in nucleotide excision repair and increased sensitivity to DNA damaging agents in melanoma cells." (PMID 28903417, 2017). "When A375 human melanoma cells were treated with 6 μM cisplatin for 48 h, an increase in the level of three NER proteins, ERCC1, XPF and XPA, was seen." (PMID 29254481, 2017). "In melanoma cell lines, the authors demonstrated that high XPF and ERCC1 protein levels correlate with low sensitivity to oxaliplatin." (PMID 26799424, 2016). "To investigate the mechanism of ERCC1 decrease and its functional contribution to apoptosis, we incubated our five carcinoma cell line panel with the proteasome inhibitor MG132 and confirmed ERCC1 levels are go up, similar to melanoma and sarcoma." (PMID 38272916, 2024). "An in silico screen identified the compound E-X PPI2 which could disrupt the ERCC1/XPF interaction, disrupt DNA repair mediated by ERCC1/XPF, and sensitize a melanoma cell line to cisplatin." (PMID 30400270, 2018). "We exploited the ability of a peptide containing this C-terminal domain to destabilise both endogenous ERCC1 and XPF in human melanoma cells and fibroblasts, resulting in reductions of up to 85% in nucleotide excision repair and near two-fold increased sensitivity to DNA damaging agents." (PMID 28903417, 2017). "Increased levels of ERCC1-XPF endonuclease activity could also facilitate increased repair of cisplatin-induced ICLs by HRR during S phase, but melanoma cells show strong transcriptional downregulation of the key HRR protein RAD51 in response to cisplatin?" (PMID 29254481, 2017). "We have previously validated ERCC1 as a therapeutic target in melanoma, but all small molecule ERCC1-XPF inhibitors reported to date have lacked sufficient potency and specificity for clinical use." (PMID 28903417, 2017). "We have also observed the presence of the larger ERCC1 transcript in other human cells such as melanoma, keratinocyte and fibroblast cells (Data not shown)." (PMID 29156754, 2017). "We found that several HRR-associated genes, including DDB2, RAD51, BRCA1, XRCC2 and BRCA2, are overexpressed in melanoma cells compared to primary melanocyte cultures, while the expression of the NER-associated genes XPA, ERCC1 and ERCC4 showed no clear differences." (PMID 32719412, 2020). "Furthermore, one of the catechol-based ERCC1-XPF inhibitors (13 compounds) showed higher activity in NER and selectivity against deoxyribonuclease I and Flap structure-specific endonuclease 1 (FEN-1) in A375 melanoma cells, resulting in improved cisplatin activity." (PMID 37062547, 2023).
melanoma (continued). "Additionally, one of the investigated catechol-based inhibitors of ERCC1-XPF (13 compound) displayed high activity in NER and selectivity against deoxyribonuclease I and Flap structure-specific endonuclease 1 (FEN-1), which resulted in enhanced cisplatin activity in A375 melanoma cells." (PMID 32370233, 2020). "Instead we chose to investigate the relationship between ERCC1-XPF and the response to cisplatin in melanoma -a cancer notoriously resistant to chemotherapy." (PMID 28903417, 2017). "However, while the final compound was shown to directly bind ERCC1/XPF and had favourable ADMET properties, it failed to sensitize melanoma cells to cisplatin." (PMID 36046263, 2020). "In addition to the evidence supporting ERCC1 as a biomarker of platinum chemoresistance, our previous research has shown that the GGR damage detection branch of NER, does not function correctly in melanoma." (PMID 29373959, 2018).
glioma (26 papers, 2003 to 2025). A benign or malignant brain and spinal cord tumor that arises from glial cells (astrocytes, oligodendrocytes, ependymal cells). "Hypermethylation has been found in the ERCC1 gene promoter in some glioma cells and is associated with suppressed ERCC1 gene expression." (PMID 33291532, 2020). "Polymorphisms in the ERCC1 gene have been shown to influence glioma susceptibility and it has previously been demonstrated that the frequency of these polymorphisms varies by ethnicity." (PMID 27135830, 2016). "By subgroup analysis, ERCC1 rs3212986 AA genotype was found to be significantly correlated with increased glioma risk in Chinese population (OR=1.37, 95%CI=1.07, 1.55) (Figure-I)." (PMID 25674148, 2014). "Our meta-analysis found that ERCC1 8092 AA genotype was significantly associated with increased risk of glioma compared with CC genotype, and the pooled OR (95%CI) was 1.29(1.07-1.55)." (PMID 25674148, 2014). "Overall, ERCC1 C8092A polymorphism was associated with the risk of glioma (AA vs. CC: OR = 1.29, 95%CI: 1.07–1.55, P = 0.01; recessive model: OR = 1.29; 95% CI: 1.07–1.55, P = 0.01)." (PMID 24763305, 2014). "In the seven studies, the frequency of ERCC1 8092A allele was 27.08% for glioma cases and 25.45% for controls." (PMID 24763305, 2014). "In conclusion, our meta-analysis suggested that ERCC1 8092AA genotype was associated with the higher susceptibility of glioma in the Chinese population." (PMID 24763305, 2014). "Remarkably, none of the original researches in Chinese populations reported the significant association between ERCC1 C8092A polymorphism and the risk of glioma." (PMID 24763305, 2014). "Genetic elements, like SNPs, comprise an essential function in altering glioma risk, such as excision repair cross-complementation group 1 (ERCC1), SNPs in X-ray repair cross-complementing protein 1, vascular endothelial growth factor (VEGF) genes, and interleukin-8." (PMID 39834980, 2024). "Risk of glioma proved to be increased in the ERCC1 C8092A variant genotype." (PMID 33266377, 2020). "Methylation of ERCC1 is associated with cisplatin sensitivity in glioma cell lines." (PMID 26967246, 2016). "The AA genotype of ERCC1 C8092A might be associated with a higher risk of adult glioma than the CA and CC genotypes and that the risk allele of ERCC2 K751Q confered a significant susceptibility to adult glioma, especially in Asian populations." (PMID 26249370, 2015). "This meta-analysis suggested that the AA genotype of ERCC1 C8092A polymorphism might increase the susceptibility of glioma in the Chinese population." (PMID 24763305, 2014). "Another study in the Caucasian population observed that ERCC1 C8092A polymorphism was associated with risk of glioma in recessive model (AA versus CC/CA: OR = 1.86, 95%CI: 1.01–3.46), however, no significant findings were reported in other studies in the Caucasian or other ethnic populations." (PMID 24763305, 2014). "We identified 30 eligible studies investigating the PubMed records (up to January 2024) via a mishmash of the subsequent terms: brain tumors, glioma, glioblastoma, gene associations, SNPs, XRCC1, XRCC3, ERCC1, and ERCC2." (PMID 39834980, 2024). "We conducted a comprehensive meta-analysis with the aim of investigating the ERCC1 (rs3212986), ERCC2 (rs13181), XRCC1 (rs25487), and XRCC3 (rs861539) genes to see if there are any risk factors for glioma susceptibility." (PMID 39834980, 2024). "We collected eligible studies together to evaluate the association between ERCC1, ERCC2, XRCC1, and XRCC3 polymorphisms and glioma risk in the present study." (PMID 39834980, 2024). "We conducted a comprehensive meta-analysis to investigate the ERCC1 (rs3212986), ERCC2 (rs13181), XRCC1 (rs25487), and XRCC3 (rs861539) genes to see if they are any risk factors for glioma susceptibility." (PMID 39834980, 2024).
glioma (continued). "Our meta-analysis included 30 articles and thus constituted a wide-ranging evaluation of the relationships of ERCC1 C8092A, ERCC2 Lys751Gln, XRCC1 Arg399Gly, and XRCC3 T241M polymorphisms with the risk of glioma in various populations." (PMID 39834980, 2024). "Variations in genes involved in DNA repair, cell cycle, metabolism, and inflammation pathways have been recognized as a key basis of inherited glioma susceptibility, such as PRKDC, XRCC1, PARP1, ERCC1, ERCC2, EGF, and IL13." (PMID 36733406, 2023). "Decreased methylation levels in the ERCC1 promoter region lead to up-regulation of the expression of ERCC1, which in turn leads to the development of glioma resistance to cisplatin treatment." (PMID 35674307, 2022). "Regarding major nodes in the DNA repair network, ERCC1, FANCD2, and RAD17 have been associated with therapy resistance in gliomas and other tumor types." (PMID 31969990, 2020). "The chemosensitive effect of siRNA targeting Ercc1 was assessed in Nude mice carrying human glioma xenografts in 3 independent experiments." (PMID 26336131, 2015). "Evidently, numerous studies have been done to identify the association of ERCC1 C8092A and ERCC2 Lys751Gln polymorphisms with the risk of glioma in different ethnic populations." (PMID 24763305, 2014). "The data from meta-analysis showed a significant increase in frequency of ERCC1 8092AA genotype in glioma patients than in controls, indicating that ERCC1 8092AA genotype contribute to increases the risk of glioma with combined OR of 1.29 (1.07–1.55)." (PMID 24763305, 2014). "Among the 10 selected studies, seven studies reported ERCC1 C8092A, including 2,936 glioma cases and 4,017 controls." (PMID 24763305, 2014). "In this study, we performed a meta-analysis of the available studies in different ethnic populations to evaluate the effects of ERCC1 C8092A and ERCC2 Lys751Gln polymorphisms on the susceptibility to glioma." (PMID 24763305, 2014). "Several previous studies have reported the role variant of ERCC1 rs3212986 and ERCC2 rs13181 polymorphisms in the risk of glioma, but the results of these studies are inconsistent." (PMID 25674148, 2014). "Our study suggests that ERCC1 rs3212986 and ERCC2 rs13181 showed different effect on the risk of glioma across different populations." (PMID 25674148, 2014). "Meta-analysis of the association of ERCC1 C8092A and ERCC2 Lys751Gln polymorphism with the risk of glioma." (PMID 24763305, 2014). "When conducting stratified analysis by ethnicity, ERCC1 rs3212986AA, ERCC2 rs13181 GT and TT genotypes was associated with increased risk of glioma in Chinese population." (PMID 25674148, 2014). "Among these genes, excision repair cross-complementing group 1 (ERCC1) and ERCC2 gene are considered to be related with the susceptibility of glioma due to their roles as rate limiting enzymes in association to NER." (PMID 24763305, 2014). "There was no significant heterogeneity between pooled studies, and thus we performed a fixed-effect model to assess the association between ERCC1 rs3212986 and ERCC2 rs13181 and risk of glioma." (PMID 25674148, 2014). "Furthermore, they found differences in the methylation levels of the ERCC1 promoter region between cisplatin-resistant human glioma tissues and cisplatin-sensitive human glioma tissues in subsequent studies." (PMID 35674307, 2022). "ERCC1 (excision repair cross-complementation group 1) was methylated in 37.5% of gliomas." (PMID 26967246, 2016). "ERCC1 is a DNA repair gene whose protein product plays an important role in nucleotide excision repair; both its protein and mRNA expression is reduced in colon cancer and glioma." (PMID 27410681, 2016). "Furthermore, an ercc-1 siRNA-based adjuvant treatment was able to improve the efficacy of TMZ in glioma tumor bearing mice." (PMID 26336131, 2015). "Therefore, an increasing amount of studies attempt to identify the association of ERCC1 and ERCC2 polymorphisms on the susceptibility of glioma." (PMID 24763305, 2014).
glioma (continued). "Therefore, we aimed to conduct a meta-analysis to investigate the role of ERCC1 rs3212986 and ERCC2 rs13181 on the risk of glioma." (PMID 25674148, 2014). "It was shown that in adults, the most common malignant tumors of neuroepithelial tissues are associated with the nucleotide excision repair genes XPD, ERCC1 and a gene located in the same (19q13.2-3) region of the chromosome - GLTSCR1 (glioma tumor suppressor candidate of an unknown function)." (PMID 22649665, 2010). "Thus, a screening test that will include the ERCC1 (rs3212986), ERCC2 (rs13181), XRCC1 (rs25487), and XRCC3 (rs861539) genes may well be helpful for the prevention and earliest treatment of patients with glioma susceptibility." (PMID 39834980, 2024). "RT‐qPCR and Western blotting methods were performed to determine the expression of PAICS, ERCC1 and XPA genes in glioma tissues." (PMID 34173716, 2021). "Out of the 13 signature genes, ATP6V1E1, EIF3D, ERCC1, GPNMB, MTDH, PCNA and NEDD9 have been reported to play crucial roles in various pathways and mechanism of glioma." (PMID 31632497, 2019). "We have identified and functionally validated that Ercc1, Ercc2, Mutyh and Pnkp participate to TMZ resistance in gliomas." (PMID 26336131, 2015). "ERCC1 plays a pivotal role in the NER pathway, which is triggered by chemotherapeutic agents that induce DNA damage in cancer cells to effectively eliminate gliomas." (PMID 37891669, 2023). "Therefore, which gene, such as HDAC7, ERCC1, LTBP4 and ZNF383, could play a major role in glioma proliferation need further study and investigation." (PMID 30691485, 2019).
squamous cell carcinoma (23 papers, 2007 to 2023). A carcinoma arising from squamous epithelial cells. "We found that ERCC1 rs735482 in the recessive model was significantly related to pathological type, being least common among patients with squamous cell carcinoma." (PMID 35069899, 2022). "In patients with squamous cell carcinoma, the expression of ERCC1 predicts a lower response to chemotherapy treatment." (PMID 32167697, 2020). "Consistent with findings from other studies, median ERCC1 levels tended to be lower in adenocarcinoma (median 0.0104) than in squamous carcinoma (median 0.0118; n.s.)." (PMID 24205040, 2013). "Those with squamous cell carcinoma of the hypopharynx/larynx were found to have marginal lower expression of ERCC1." (PMID 21426588, 2011). "It has been reported that a high ERCC1 expression may predict cisplatin-based chemotherapy resistance and poor outcome in unresectable squamous cell carcinoma of the head and neck." (PMID 33029487, 2020). "Increased expression of Excision repair cross-complementation group 1 (ERCC1) correlated with a better prognosis of cervical cancer and ERCC1 expression was a useful predictive marker of locally advanced squamous cell carcinoma of the head and neck in patients treated with cisplatin." (PMID 29632637, 2018). "All the samples selected were ERCC1 positive, including 6 squamous carcinoma and 6 adenocarcinoma." (PMID 22439756, 2012). "ERCC1 expression is e.g. higher in squamous cell carcinoma compared to adenocarcinoma." (PMID 21961533, 2011). "Squamous cell carcinoma of the head and neck of the hypopharynx showed higher expression of ERCC1." (PMID 18594541, 2008). "We investigated the relationship between peripheral blood RRM1, ERCC1, and BRCA1 expression levels with histopathology classifications (squamous cell carcinoma, adenocarcinoma), smoking, age, clinical staging (IIIB and IV), and chemotherapy response." (PMID 24591771, 2014).